FOXO1 (forkhead box O1)
Diseases named in the same sentence as FOXO1 in open-access papers (continued):
Sharing a sentence is not in itself a finding about the gene and the disease.
astrocytomas (1 paper, 2013). "Thus, both high cytoplasmic expression of FOXO1 and pFOXO1 were associated with malignant characteristics of astrocytomas." (PMID 23874926, 2013). "Our study analyzed the expression of FOXO1 and pFOXO1 protein and their biological significance in human astrocytoma for the first time, which demonstrated that high cytoplasmic FOXO1 and pFOXO1 expression were associated with higher WHO grade and a worse prognosis." (PMID 23874926, 2013). "Nuclear FOXO1 expression in astrocytoma cells (median H-score 40, 0–285) was also significantly higher than normal brain tissue (median H-score 3, 0–60) (P = 0.001)." (PMID 23874926, 2013). "Our study showed that higher cytoplasmic FOXO1 and pFOXO1 protein expression correlate with poor survival of astrocytoma patients, which is consistent with its inactivation by phosphorylation and cytoplasm translocation." (PMID 23874926, 2013). "In conclusion, our study demonstrated that cytoplasmic expression of FOXO1 and pFOXO1 are elevated in astrocytomas and are increased with higher grade." (PMID 23874926, 2013). "Nuclear pFOXO1 level was significantly higher than that of FOXO1, which indicated the phosphorylation of FOXO1 is probably critical in the genesis of astrocytomas." (PMID 23874926, 2013). "We therefore evaluated FOXO1 and pFOXO1 protein expression in 181 primary astrocytoma samples and 16 normal brain samples." (PMID 23874926, 2013). "In this study, we examined expression of FOXO1 and pFOXO1 protein in a large cohort of astrocytomas using tissue microarray (TMA) technology and analyzed for their correlations with clinical characteristics as well as disease progression." (PMID 23874926, 2013). "In multivariate analysis, high cytoplasmic FOXO1 and pFOXO1 expression were independent prognostic factors for astrocytomas." (PMID 23874926, 2013). "The median H-score for cytoplasmic FOXO1 was 55 (range, 0–285) in astrocytoma samples, which was significantly higher than that of normal brain tissue samples (median H-score 5, range 0–160) (P = 0.036)." (PMID 23874926, 2013). "Nuclear pFOXO1 level was significantly higher than nuclear FOXO1 in astrocytomas." (PMID 23874926, 2013). "Moreover, both high cytoplasmic FOXO1 and pFOXO1 are independent prognosis factors for astrocytoma patients." (PMID 23874926, 2013). "Astrocytoma samples expressed higher cytoplasmic FOXO1 and pFOXO1 than normal brain samples." (PMID 23874926, 2013). "Due to the following aspects, FOXO1 and pFOXO1 could be good prognosis factors in astrocytomas." (PMID 23874926, 2013). "Thus, our data suggested that cytoplasmic FOXO1 and pFOXO1 expression may serve as valuable prognostic variables in astrocytomas and may have significant implications for the development and application of targeted therapy." (PMID 23874926, 2013).
autoimmune uveitis (1 paper, 2024). An autoimmune form of uveitis (disease). "Apremilast (a phosphodiesterase-4 inhibitor) was found to regulate Th17 and Treg cells by inhibiting the phosphorylation of the PI3K/Akt/Forkhead Box O1 (FoxO1) signaling pathway, thereby alleviating experimental autoimmune uveitis (EAU)." (PMID 39736777, 2024).
Barrett's oesophagus (1 paper, 2007). "To further characterise the downstream effectors of Akt activation in Barrett's oesophagus we examined the effects of acid and leptin on the phosphorylation of the pro-apoptotic protein Bad and the FKHR transcription factor FOXO1." (PMID 17559672, 2007).
brain hemorrhage (1 paper, 2022). "CCL17 depended on CCR4 activation regulating the PI3K/AKT/FOXO1 signaling pathway to reduce neuronal inflammation and apoptosis after brain hemorrhage." (PMID 35800988, 2022).
breast adenocarcinoma (1 paper, 2019). "The grade of FOXO1 expression was correlated with the TRIB3 expression in tumor tissues based on immunohistochemistry analysis of human tumor tissue microarrays of breast adenocarcinoma." (PMID 31844113, 2019).
bronchopulmonary dysplasia (1 paper, 2025). Bronchopulmonary dysplasia is a chronic respiratory disease that results from complications related to lung injury during the treatment of infant acute respiratory distress syndrome in low-birth-weight premature infants or from abnormal lung development in older infants. "The activation of FOXO1 has been demonstrated tosuppress oxidative stress-induced apoptosis of epithelialcells in a model of bronchopulmonary dysplasia (Zanget al., 2023)." (PMID 41164273, 2025).
carcinoid syndrome (1 paper, 2020). "In pathological conditions of high 5-HT levels, as observed in carcinoid syndrome, the association between FOXO1 and CREB is disrupted, favoring the formation of ATF4-FOXO1 heterodimers that resulted in an upregulation of the ATF4-mediated responses." (PMID 32276412, 2020).
cervical tumors (1 paper, 2022). "Previous studies have shown that FOXO1 expression is ablated in cervical tumors compared to normal tissue, and that FOXO1 expression decreases as precancerous lesions progress." (PMID 36497200, 2022).
Chiari malformation (1 paper, 2024). A rare genetic brain malformation characterized by displacement of the brain stem and cerebellum through the foramen magnum. "This correlation is further substantiated by a study showing that another Wnt negative regulator, FOXO1, can cause Chiari malformation, which was observed in a child with lambdoid craniosynostosis." (PMID 39168120, 2024).
chondrodysplasia (1 paper, 2024). "Specifically, FoxO1 and FoxO3a exert chondroprotective effects crucial for maintaining cartilage homeostasis, whereas dysfunctional FoxO1 and FoxO3a might contribute to chondrodysplasia." (PMID 38886174, 2024).
chondrosarcoma (1 paper, 2015). A malignant cartilaginous matrix-producing mesenchymal neoplasm arising from the bone and soft tissue. "We then analyzed FOXO1 expression in five human OS cell lines and one chondrosarcoma cell line." (PMID 26344693, 2015).
chordoma (1 paper, 2025). Chordomas are rare malignant tumors arising from embryonic remnants of the notochord in axial skeleton. "The lesion was again subtotally resected, and histopathology revealed dedifferentiated chordoma with rhabdomyosarcomatous differentiation (G3); no FOXO1 rearrangement was found." (PMID 41420192, 2025).
chorioamnionitis (1 paper, 2018). A morphologic finding indicating inflammation of the fetal sac membranes. "The differential expression of FoxO1 protein according to the presence or absence of acute chorioamnionitis in the thymic medulla, but not in the thymic cortex, is intriguing." (PMID 29083107, 2018). "When FoxO1 protein expression was assessed using a four‐tiered grading system (0, 1+, 2+, 3+), the cases with acute chorioamnionitis showed a significantly decreased FoxO1 immunoreactivity in the medullary thymus than did those without acute chorioamnionitis did (P = 0.015)." (PMID 29083107, 2018).
chronic heart failure (1 paper, 2020). "Aberrant Wnt/β-catenin signaling causes a shift in muscle fiber type through the interaction of Wnt3a with FOXO1 in chronic heart failure in mice." (PMID 33334063, 2020).
chronic myelomonocytic leukemia (1 paper, 2023). A myelodysplastic/myeloproliferative neoplasm which is characterized by persistent monocytosis, absence of a Philadelphia chromosome and BCR/ABL fusion gene, fewer than 20 percent blasts in the bone marrow and blood, myelodysplasia, and absence of PDGFRA or PDGFRB rearrangement. "To test the activation of FOXO1-controlled genes in vivo, we took advantage of patients suffering from chronic myelomonocytic leukemia (CMML) and treated with HU." (PMID 36869180, 2023). "Notably, the treatment of chronic myelomonocytic leukemia (CMML) patients with hydroxyurea (HU) activates the NF-κB and FOXO1 pathways in proliferating cells, revealing the activation of this pathway in vivo." (PMID 36869180, 2023).
coagulopathy (1 paper, 2025). "The involvement of JUN, FOXO1, and MAPK3 in complement and coagulation cascades suggests their potential role in immune-mediated inflammation and coagulopathy, which are frequently observed in HIV-infected individuals." (PMID 40574839, 2025).
complication (1 paper, 2020). Any disease or disorder that occurs during the course of, or because of, another disease, treatment, or procedure. "This is suggestive of FoxO1 alteration as a major contributing factor to the development of diabetic vascular complications." (PMID 33108705, 2020). "Therefore, we investigated the role of FoxO1 in the pathological progress of diabetic vascular complications." (PMID 33108705, 2020).
congenital toxoplasmosis (1 paper, 2025). Toxoplasma infection that is present from birth. "Further investigation using ex vivo human placental models combined with experimental models of congenital toxoplasmosis in mice deficient for Foxo3 and Foxo1 in the uterine compartment will help shed light on this matter." (PMID 41450565, 2025).
coronary atherosclerosis (1 paper, 2022). Atherosclerosis of the coronary vasculature. "Shi and Chen demonstrated the regulatory effects of miR-370 in coronary atherosclerosis by targeting the forkhead box protein O1 (FOXO1) gene." (PMID 36012267, 2022). "Up-regulation of miR-370 in patients with coronary atherosclerosis hindered cellular apoptosis by reducing the expression of the FOXO1 gene and enhancing endothelial cell migration and invasion." (PMID 36012267, 2022).
cyst (1 paper, 2012). A sac-like closed membranous structure that may be empty or contain fluid or amorphous material. "FoxO1-ADA expression in those ductal cells can be speculated to cause cyst formation in the pancreas of TG mice." (PMID 22384192, 2012).
deficiencies (1 paper, 2012). "In order to identify additional factors that contribute to human congenital hormone deficiencies, we are investigating the forkhead transcription factor, FOXO1, which has been implicated in development of several organs including ovary, testis, and brain." (PMID 23251696, 2012).
developmental delay (1 paper, 2021). "FOXO1, FOXO3, and FOXO4 proteins are localized in the cytoplasm during embryo development and are located in the nucleus in embryos with developmental delay." (PMID 33540675, 2021).
Duchenne muscular dystrophy (1 paper, 2023). Duchenne muscular dystrophy (DMD) is a neuromuscular disease characterized by rapidly progressive muscle weakness and wasting due to degeneration of skeletal, smooth and cardiac muscle. "We also tested the antineoplastic activity of piperacetazine in a second mouse model where PAX3::FOXO1 is expressed under a doxycycline-regulated promoter in an immortalized human Duchenne muscular dystrophy myoblast cell line (Dbt) expressing MYCN." (PMID 37732905, 2023).
folate deficiency (1 paper, 2020). A nutritional condition produced by a deficiency of FOLIC ACID in the diet. "We sought to determine the involvement of the Akt/FOXO1/Bim signaling pathway in folate deficiency-induced apoptosis." (PMID 33372619, 2020). "However, little is known as to whether FOXO1 participates in folate deficiency-induced cell apoptosis." (PMID 33372619, 2020). "Additionally, treatment with LY294002 inhibitor revealed the involvement of the Akt/FOXO1/Bim signaling pathway in folate deficiency-induced apoptosis, rather than the ERK pathway." (PMID 33372619, 2020).
gastric adenocarcinoma (1 paper, 2013). "miR-27a has been shown to function as oncogenes in gastric adenocarcinoma by targeting prohibitin and forkhead box protein O1 (FOXO1), which could protect cells against oxidative stress." (PMID 23613822, 2013).
gastric ulcer (1 paper, 2024). An ulcerated lesion in the mucosal surface of the stomach. "This study aims to evaluate the gastroprotective effects of free hesperidin and its chitosan nanoparticles (HNPs) against ethanol-induced gastric ulcers in rats, focusing on the Sirt-1/FOXO1/PGC-1α/HO-1 signaling pathway." (PMID 39314751, 2024).
gliosarcoma (1 paper, 2018). A rare histological variant of glioblastoma (WHO grade IV) characterized by a biphasic tissue pattern with alternating areas displaying glial and mesenchymal differentiation (WHO). "Examination of another secondary gliosarcoma culture in our collection, SGS2, similarly showed significant downregulation of CEBPA and FOXO1." (PMID 29416795, 2018). "Significantly downregulated transcription factors common to both gliosarcomas were HOXA5, FOXO1, and CEBPA." (PMID 29416795, 2018).
gynecological cancers (1 paper, 2025). "In certain gynecological cancers, SIRT1 deacetylated both FOXO1 and FOXO3a, reducing their pro-apoptotic and anti-proliferative effects and increasing proliferation and survival." (PMID 41300302, 2025).
HCMV infection (1 paper, 2022). "Turning to protein expression, we were intrigued to observe that FoxO3a and FoxO1 protein levels were strongly upregulated during HCMV infection." (PMID 35946797, 2022).
head and neck cancer (1 paper, 2017). A primary or metastatic malignant neoplasm affecting the head and neck. "Specifically, we showed that an activating PIK3CA mutation altered FOXO1 activity in the BRCA model but not in the head and neck cancer model, consistent with the context-specific predictions of our algorithm." (PMID 28139702, 2017). "Our analysis associated mutant PIK3CA with ELK1 and TCF4 activity in both breast and head and neck cancer, and with FOXO1 activity in BRCA but not in head and neck cancer." (PMID 28139702, 2017).
hyperandrogenism (1 paper, 2021). Excessive secretion of androgens from the adrenal glands or gonads. "Moreover, the changes in FoxO1-mediated signaling may further induce the occurrence of low-grade chronic inflammation in the body, thereby leading to the hyperandrogenism of PCOS." (PMID 33746783, 2021).
hyperlipemia (1 paper, 2018). "Our study here shows that FcγRIIb knockdown and knockout increase the insulin-induced phosphorylation of AKT and FOXO1 in HepG2 and the animal model, suggesting that FcγRIIb inhibits insulin-induced activation of AKT and FOXO1, and in turn upregulates G6Pase and PEPCK in hyperlipemia in hepatocytes." (PMID 30261661, 2018).
intracranial aneurysm (1 paper, 2022). "The complementary pairing of KDR mRNA is mir-370-3p, which regulates the activity of the AKT/FOXO1 signaling pathway involved in intracranial aneurysm." (PMID 35800988, 2022).
Iron deficiency anemia (1 paper, 2024). "Recent studies have indicated that vitamin D/VDR can downregulate the expression of FOXO1 in diabetic patients, inhibiting iron-deficiency anemia in pancreatic β-cells." (PMID 38978780, 2024).
ischemic disease (1 paper, 2024). Lack of blood supply to an area of the body, resulting in impairment of tissue oxygenation. "Collectively, our data uncover that F2 pretreatment exerts significant protection against post ischemic myocardial injury by its regulation of AMPK/FoxO1 pathway, which may provide a new avenue for treating ischemic disease." (PMID 37987145, 2024).
joint diseases (1 paper, 2025). "In chondrocytes, the PI3K/AKT/FOXO1 pathway may play a similar role in the onset of OA, thus providing a molecular basis for the connection between metabolic disorders and joint diseases." (PMID 41013182, 2025).
Kaposi's sarcoma (1 paper, 2020). A malignant neoplasm characterized by a vascular proliferation which usually contains blunt endothelial cells. "Consistent with our result, FOXO1 inhibition also induced HIV and Kaposi’s sarcoma-associated herpes virus replication in cells by inducing intracellular ROS levels." (PMID 32522961, 2020).
laminopathies (1 paper, 2021). "A recent study revealed that phosphorylated (inactive) FoxO1 level was reduced and the nuclear localization of FoxO1 was increased in the mouse heart with laminopathies." (PMID 34522203, 2021).
latent infection (1 paper, 2023). "In this study, we found that KSHV latent infection of B lymphoma cells significantly enhance the antioxidant capacity by upregulating both forkhead box protein O1 (FoxO1) and FoxO3." (PMID 37594999, 2023). "Consistently, KSHV latent infection slightly upregulated FoxO1 while dramatically upregulated FoxO3 in BJAB cells." (PMID 37594999, 2023). "We have recently reported that KSHV latent infection significantly upregulate FoxO1 and FoxO3 to ablate oxidative stress in KSHV-transformed cells." (PMID 37594999, 2023). "We found that KSHV latent infection slightly while robustly upregulates FoxO1 and FoxO3, respectively, which is essential for KSHV-positive B lymphoma cells to defend oxidative stress." (PMID 37594999, 2023). "Mechanistically, we identified forkhead box protein O1 (FoxO1) and FoxO3 as irrevocable antioxidant defense genes and both of them are upregulated by KSHV latent infection, which is essential for the promoted ROS scavenging in KSHV-positive B lymphoma cells." (PMID 37594999, 2023). "Here we identified FoxO1 and FoxO3 as the key antioxidant genes and KSHV latent infection upregulated both of them, which helps PEL cells to resist oxidative stress." (PMID 37594999, 2023). "Moreover, the protein expression of both FoxO1 and FoxO3 was robustly increased following KSHV latent infection of rat primary metanephric mesenchymal precursor (MM) cells." (PMID 37594999, 2023).
Legionnaires' disease (1 paper, 2021). A pneumonia caused by Legionella pneumophila and other Legionella species, which is characterized by fever, cough, progressive respiratory distress, and which is often accompanied by extrapulmonary manifestations. "Meanwhile, FOXO1 could regulate the promoter activity of coronin-1 and the FOXO1/coronin-1 axis could be used as a novel candidate signaling pathway for the treatment of Legionnaires' disease." (PMID 34812410, 2021).
Leigh syndrome (1 paper, 2013). A progressive neurological disease defined by specific neuropathological features associating brainstem and basal ganglia lesions. "Another differentially regulated gene of particular interest in RC disease was LRPPRC, which is known to interact with FOXO1 and PGC-1alpha proteins and is mutated in French-Canadian Leigh syndrome with RC complex IV deficiency." (PMID 23894440, 2013).
limb ischemia (1 paper, 2021). A ischemia that involves the limb. "In conclusion, our study indicates that the utilization of RSV could reduce the activity and alter the cellular distribution of FoxO1, which would improve collateral vessels formation and limb ischemia." (PMID 34946610, 2021).
lung diseases (1 paper, 2015). "TCF7 interacts with multiple proteins and target genes (e.g. CD3E, β-catenin, TCF7L2, LEF-1, IL-17, IL-4, or Eomes) and is involved in several signal pathways (e.g. Wnt, FoxO1, Notch, or P21pathways) which are critical for lung diseases, especially the canonical Wnt/β-catenin pathway." (PMID 26289446, 2015).
lung neoplasm (1 paper, 2024). A benign or malignant, primary or metastatic neoplasm involving the lungs. "The results showed that FOXO1 may be associated with radiation responses in lung neoplasms and head and neck neoplasms." (PMID 38406264, 2024).
lymphatic disorders (1 paper, 2024). "Furthermore, whether compound genetic variants in genes in the PIEZO1/ANGPT2/TIE/FOXO1 pathway predispose to lymphatic disorders in humans was not explored here and remains an interesting path for future investigation." (PMID 38747287, 2024).
male infertility (1 paper, 2025). The inability of the male to effect fertilization of an ovum after a specified period of unprotected intercourse. "Loss of Foxo1 in embryonic gonocytes leads to defective spermatogenesis in adulthood, and inactivation of Foxo1 in spermatogonia results in germ cell loss and male infertility." (PMID 40063068, 2025).